BATF (basic leucine zipper ATF-like transcription factor)
Diseases named in the same sentence as BATF in open-access papers (continued):
Sharing a sentence is not in itself a finding about the gene and the disease.
sarcoidosis (1 paper, 2017). Sarcoidosis is a multisystemic disorder of unknown cause characterized by the formation of immune granulomas in involved organs. "Microarray analysis of sarcoidosis PBMC revealed a positive correlation between the expression of PDCD1, the gene encoding PD-1, and basic leucine zipper transcription factor ATF-like (BATF) (r = 0.58, p = 0.005)." (PMID 29234685, 2017). "Analysis of BATF transcript and PD-1 protein expression in sarcoidosis CD4+ T cells revealed a positive relationship between BATF and PD-1, such that sarcoidosis subjects with high PD-1 upregulation also express higher levels of BATF (r = 0.56, p = 0.02)." (PMID 29234685, 2017).
tuberculosis (1 paper, 2019). A chronic, recurrent infection caused by the bacterium Mycobacterium tuberculosis. "Notably, we also found that the expression of BATF was significantly increased with increasing PD-1 expression on the surface of T cells in the context tuberculosis." (PMID 31681314, 2019). "Therefore, the role of BATF in tuberculosis deserves further investigation." (PMID 31681314, 2019). "A clinical study analyzed 7 cases of ATB and 8 cases of LTBI and found that gene BATF was much lower in ATB patients than LTBI cases, suggesting that BATF may provide new insights for the diagnosis of tuberculosis." (PMID 31681314, 2019).
tumor (66 papers, 2014 to 2026). "In our previous research on CAR-T cell-mediated elimination of AML tumor cells, we found that BATF downregulation and EGR1 upregulation are closely associated with reduced CAR-T cell exhaustion and enhanced cell functionality." (PMID 40225861, 2025). "As demonstrated by a previous publication, REGNASE-1 deficiency reprograms CD8+ T cells in the tumor by enhancing BATF, resulting in improving mitochondrial metabolism, which is reversed upon BATF deletion." (PMID 33809259, 2021). "We conclude that separating the ABC-DLBCL subset according to relative expression of the two IRF4 cofactors SPIB and BATF identifies subgroups differentially linked to previously defined features of DLBCL tumour biology." (PMID 24875472, 2014). "Additionally, BATF-deficient tumor-reactive CD8+ T cells had significantly lower expression of granzyme B, a cytolytic molecule produced by effector lymphocytes." (PMID 33809259, 2021). "Analysis of immunologic gene signature and hallmark gene sets revealed that BATF-overexpressing tumor-specific CD8+ T cells found in the tumor exhibited a transcriptional profile consistent with higher effector, higher memory, and lower exhausted gene expression profiles." (PMID 33809259, 2021). "This was validated by qPCR showing higher BATF expression in CD8+ T cells derived from the tumor tissuethan that in the normal tissue." (PMID 41194450, 2026). "Tumor fragments derived from subcutaneous xenografts established using HGC-27 cells with SLC39A5 knockdown alone or in combination with BATF OE." (PMID 40992658, 2025). "The knockdown of SLC39A5 alone inhibited tumor growth of nude mice, whereas OE of BATF promoted tumor growth, mitigating the effects of SLC39A5 knockdown." (PMID 40992658, 2025). "Regulators associated with tumorigenesis and tumor progression, such as EGR1, FOSL, BATF, and HOXB3, were enriched in malignant clusters." (PMID 39872221, 2025). "Gross examination of the stomachs revealed markedly smaller orthotopic tumors in the sh-SLC39A5 group compared with controls, whereas BATF OE partially rescued tumor growth." (PMID 40992658, 2025). "In Zhang's study, BATF was shown to drive T cell exhaustion under conditions of low T cell-to-tumor cell ratios and repeated tumor antigen stimulation, which is an exhaustion-inducing microenvironment." (PMID 40093905, 2025). "In EBV-infected B-cells, IRF4 and BATF jointly repress tumor suppressors like PRDM1 and BCL2L11, thereby promoting transformation." (PMID 40313738, 2025). "BATF plays a key role in T cell exhaustion and tumor immune evasion, processes that are pivotal in cancer progression." (PMID 40315269, 2025). "Previous research has confirmed that BATF expression plays a significant role in the tumour microenvironment." (PMID 39872530, 2024). "In CRC patients, BATF expression was upregulated in tumor tissues compared with matched para-tumoral tissues, and was related with gender and Ki-67 levels." (PMID 38862971, 2024). "This suggests a potential mechanism by which BATF overexpression in anti-tumour CD8+ T cells generates robust responses." (PMID 39399500, 2024). "Regulatory T cells (Tregs, CD4_cluster2) with FOXP3, CTLA4, ICOS, and BATF expression were also abundant, which has been demonstrated as tumor-specific alterations in the tissue microenvironment." (PMID 39514276, 2024). "In Tregs, BATF plays a more significant role in regulating the transcriptional networks of tumour-restricted suppressive Tregs." (PMID 38581063, 2024). "The deletion of BATF in CD8+ T cells impaired tumour clearance, while BATF overexpression promoted the effector function, improving tumour control independently of CD4+ helper T cells." (PMID 39169517, 2024). "To improve the anti-tumor efficacy of CAR-T cells using eMIATAC, we initially focused on targeting BATF, a protein associated with T-cell exhaustion." (PMID 39113807, 2024).
tumor (continued). "Their study identified BATF as a crucial factor in the maintenance of CD8+ T‐cell effector function in tumours." (PMID 39169517, 2024). "Integrative transcriptomic and epigenomics data showed that IRF4, alone or in combination with BATF, was directly responsible for tumor immunosuppression." (PMID 38918817, 2024). "Silencing or knockdown of BATF promoted memory-like phenotypes capable of superior anti-tumour immunity in a range of ACT models, including patient-derived pancreatic carcinomas." (PMID 39399500, 2024). "Upregulation of transcription factor BATF controlled the activation program of clusters 3 and 6 in tumor and interface zones." (PMID 37644609, 2023). "We obtained the top 100 genes similar to BATF across 33 tumor types from the GEPIA2 “Similar genes” module and performed GO enrichment analysis to gain insights into the roles of BATF in tumors." (PMID 35573731, 2022). "Overall, our data show that BCYRN1 can enhance TM4SF1 expression in a BATF recruitment-dependent fashion to modulate tumor malignancy, thereby enhancing HCC cell migration, invasion, and proliferation." (PMID 35730016, 2022). "All these findings indicate that BATF acts as a vital transcriptional factor in regulating tumor immune infiltration via an immune-related pathway." (PMID 35573731, 2022). "Intriguingly, the physical interaction of BATF with the IRF4 transcription factor was essential for the improvement of anti-tumor responses and prevention of exhaustion in the tumor-specific CAR T cells." (PMID 35251035, 2022). "We next divided the tumor species into high- and low-expression groups according to median expression levels of BATF to evaluate the correlation between BATF expression and survival times of patients with tumors." (PMID 35573731, 2022). "In the present study, we first explored the expression profiles of BATF in 33 tumor types and found that BATF was aberrantly upregulated in the majority of tumors." (PMID 35573731, 2022). "Except for PRAD, tumor samples with enforced BATF expression presented with lower methylation levels compared to those measured in corresponding normal tissues." (PMID 35573731, 2022). "In other words, if CAR T-cells are steadily expressing BATF, progress in tumor immunotherapy will occur." (PMID 35573731, 2022). "The IRF8 (Interferon regulatory factor 8) and BATF (Basic Leucine Zipper ATF-Like Transcription Factor) are very crucial in developing the anti-tumour response in tumour surveillance." (PMID 35388653, 2022). "In line with our above results, BCYRN1 and BATF overexpression accelerated tumor growth, whereas TM4SF1 silencing had the opposite effect." (PMID 35730016, 2022). "The Th17 cells were converted into cells that mediate IL-9-dependent effects by STAT5 and BATF in allergic airway inflammation and anti-tumor immunity." (PMID 36138889, 2022). "To determine if BATF is intrinsically required for CD8+ T cell-mediated tumor control, we utilized a mixed bone marrow chimera (BMC) model." (PMID 33809259, 2021). "PD-1, although generally regarded as an inhibitory receptor, is also indicative of T cell activation, suggesting that BATF plays an important role in the maintenance of activated CD8+ T cells in the tumor." (PMID 33809259, 2021). "Using mixed bone marrow chimeras, we demonstrated that CD8+ T cell-specific deletion of BATF resulted in impaired tumor control." (PMID 33809259, 2021). "Our findings also indicated that, compared to empty vector controls, tumor-specific CD8+ T cells that overexpressed BATF expressed a gene set more similar to CD8+ T cells found in acute, rather than chronic, LCMV infection." (PMID 33809259, 2021). "To assess the changes in these tumor-reactive CD8+ T cells upon BATF overexpression, we conducted gene set enrichment analysis (GSEA) using gene sets from the Broad Institute’s Molecular Signatures Database (MSigDB) and the Reactome database." (PMID 33809259, 2021).
tumor (continued). "This confirmed that higher expression of several known CTCL marker genes, including CD27, IL-32, CXCL13, BATF, and TIGIT28–32, was associated with spots with higher frequencies of tumor cells (see yellow highlighted genes)." (PMID 34795254, 2021). "In summary, these findings suggest that BATF is an essential component of CD8+ T cell anti-tumor effector function." (PMID 33809259, 2021). "As our previous findings indicated, BATF overexpression enhanced tumor infiltration and function of effector CD8+ T cells within the tumors of mice treated with this adoptive cell therapy." (PMID 33809259, 2021). "The effects of the combination of caSTAT5 and BATF were also observed on analysis of tumor size and weight following excision." (PMID 32985505, 2020). "STAT5 and BATF convert Th17 cells into cells that mediate IL-9-dependent effects in allergic airway inflammation and anti-tumor immunity." (PMID 32985505, 2020). "Several predicted TFs in tumor-reactive cells have been reported to be associated with T cell exhaustion, such as NR4A1 and BATF." (PMID 31892342, 2019). "This underscores a BRD4-specific role in anti-tumor immunity, further supported by adoptive transfer studies, where BRD4 inhibition via the BRD4–p300 axis enhanced BATF expression, improving persistence and anti-tumor activity in adoptive T cell and CAR-T models." (PMID 41583469, 2025). "Likewise, in tumor models, the effects of BATF on T cell-mediated antitumor responses remain inconsistent and context-dependent." (PMID 40093905, 2025). "Tissue-resident and tumor-invasive Tregs share common differentiation and activation pathways, with most differentiation and activation of Tregs in tissues and tumors being mediated by BATF." (PMID 39876010, 2025). "Another hypothesis is that thiostrepton affects other transcription factor networks critical to Treg identity and function, such as IRF4, BATF, and Helios, which together orchestrate the effector Treg program within the tumor microenvironment." (PMID 40820379, 2025). "They showed that CAR-T cells overexpressing BATF exhibited increased effector cytokines secretion, enhanced proliferation, decreased levels of exhaustion-associated TOX, increased expansion potential and tumor rejection." (PMID 40093905, 2025). "Moreover, there is a significant positive correlation between BATF‐regulated genes (i.e., DEGs between BATF‐KO versus WT CTLs) and the RARα‐regulated genes (i.e., DEGs between RARα‐TG versus WT tumor‐infiltrating CTLs)." (PMID 40068101, 2025). "Inhibiting BATF activity may shift the tumor microenvironment from an immunosuppressive state to an immune-activated state, improving patient outcomes." (PMID 40315269, 2025). "Interestingly, studies have shown both up- and down- regulation of BATF in CD8+ T cells can improve anti-tumour immunity." (PMID 39399500, 2024). "To examine the effects of BATF expression on immune cells, we analyzed main tumor microenvironment components via flow cytometry and identified that shBATF treated cells showed a significant increase in CD8+T cells and NK cells in the bone marrow compared to control cells." (PMID 39872530, 2024). "Finally, we concatenated eMIATAC with CAR sequences to construct CAR-T cells with low BATF protein levels and verified the changes in their anti-tumor efficacy." (PMID 39113807, 2024). "We noted that a transcription factor, basic leucine zipper ATF-like transcription factor (Batf), which has been shown to play a crucial role for Treg development in the tumor microenvironment, was expressed on the Tregs_Foxp3 cluster that was remarkably expanded in dKO cells." (PMID 39405120, 2024). "Furthermore, single-cell sequencing analysis revealed AML cells with varying levels of BATF expression within the tumor microenvironment." (PMID 39872530, 2024).
tumor (continued). "CRISPR screens have discovered that TOX can promote CD8 + T cell exhaustion in collaboration with NR4A, and TOX serves as a significant downstream regulatory molecule reversing tumour-infiltrating T cell exhaustion with BATF and IRF4, which were the hits in several CRISPR screenings." (PMID 38581063, 2024). "In NBL, BATF might regulate Th cell differentiation, thereby shaping the immune landscape and influencing the immune response against tumor cells." (PMID 39559348, 2024). "Depletion of BATF decreased the number of T cells and poor tumor control." (PMID 37398660, 2023). "Tumor cells transfected with BATF siRNA significantly downregulated BATF mRNA expression." (PMID 35573731, 2022). "Hence, we investigated genetic alterations of BATF in a pan-cancer cohort containing 10,969 tumor samples." (PMID 35573731, 2022). "A pan-cancer omics analysis to explore potential roles of BATF in tumors may provide a novel strategy for tumor immunotherapy." (PMID 35573731, 2022). "In spite of the fact that BATF expression was increased in most tumors, BATF was only associated with clinicopathological stages in BLCA and KIRC, which indicated that BATF is steady during tumor progression into higher grades in other tumors." (PMID 35573731, 2022). "Previous studies reported that BATF was crucial for T cell proliferation and exhaustion; we wondered whether BATF could also regulate tumor cell viability." (PMID 35573731, 2022). "In vitro assay was also performed to explore roles of BATF in tumor cells." (PMID 35573731, 2022). "Next, we compared the expression levels of BATF in 33 tumor types and adjacent normal tissues." (PMID 35573731, 2022). "First, the exhaustion of CD8+ cells is a common cause of the failure of immunotherapy, and the cooperation of BATF with IRF4 could counter this exhaustion in tumor-infiltrating CAR T-cells." (PMID 35573731, 2022). "Similarly, BATF was also highly expressed in several tumor cells, and BATF protein was dominantly distributed in the nucleus of these cells." (PMID 35573731, 2022). "Our present results also indicated that BATF is important for tumor cell viability." (PMID 35573731, 2022). "In addition, high BATF expression was also observed in RA SF Treg cells and tumor-infiltrating Treg cells, suggesting BATF is a key transcriptional regulator in both human and mice eTreg cells." (PMID 33976194, 2021). "In addition, PD-1 Ab treatment has been shown to lead to the expansion of a CD8 T-cell cluster in the tumor, expressing Tbet+Eomes+MHCII+BATF+PD-1+TIM-3+CD27+CD69+Gata-3+ that correlated with small tumor size." (PMID 34912335, 2021). "Indeed, gene set enrichment and leading-edge analyses of activated, (shared) tissue, inflammatory and tumor-infiltrating Treg cell gene sets amongst others revealed sharing of the core eTreg cell genes, including BATF, CCND2, CCR8, TNFRSF18, and VDR." (PMID 33976194, 2021). "To better understand how BATF may regulate this enhanced effector program, we conducted bulk RNA sequencing of tumor-infiltrating, adoptively transferred transduced CD8+ T cells." (PMID 33809259, 2021). "Collectively, these findings support the idea that BATF is a key regulator of effector CD8+ T cell activity and function within the tumor and shed light on potential pathways that BATF may upregulate to facilitate effective tumor control." (PMID 33809259, 2021). "After observing the significant effects mediated by BATF overexpression, we decided to further investigate potential mechanisms by which BATF regulates CD8+ T cells by conducting transcriptional analysis of tumor-infiltrating, retrovirally transduced CD8+ T cells." (PMID 33809259, 2021). "Knocking out BATF, rather than overexpressing it, upregulated T cell activation-associated genes while suppressing exhaustion-related genes, promoting the differentiation of central memory T cells, and enhancing tumor rejection." (PMID 40093905, 2025).